TBX2 (T-box transcription factor 2)
Diseases named in the same sentence as TBX2 in open-access papers (continued):
Sharing a sentence is not in itself a finding about the gene and the disease.
breast carcinoma (continued). "Indeed, knocking down TBX2 in melanomas or in several metastatic breast cancer cell lines resulted, respectively, in induction of senescence or in a profound inhibition of proliferation, regardless of their receptor status." (PMID 32195221, 2020). "To begin to understand whether these compounds exerted their anti-cancer activity through binding TBX2, we next analyzed their cytotoxicity in TBX2 expressing breast carcinoma, melanoma and rhabdomyosarcoma cells." (PMID 32195221, 2020). "Importantly, depleting TBX2 sensitizes cisplatin-resistant breast cancer and metastatic melanoma cells to this drug." (PMID 32195221, 2020). "Furthermore, TBX2 is shown to directly repress E-Cadherin transcription, and to increase motility and invasiveness of malignant breast cancer cells." (PMID 28881763, 2017). "TBX2/3 may also contribute to breast cancer growth by promoting proliferation of cancer stem-like cells." (PMID 26579496, 2015). "TBX2/3 may also contribute to breast cancer growth by promoting the proliferation of cancer stem-like cells." (PMID 25344916, 2014). "In summary, we have identified a novel pathway regulated by the breast cancer oncogene TBX2." (PMID 24742492, 2014). "TBX2 is an oncogenic transcription factor known to drive breast cancer proliferation." (PMID 24742492, 2014). "TBX2 is also amplified and overexpressed in several human breast carcinoma cell lines." (PMID 22844464, 2012). "The prognostic significance of TBX2 in human breast cancer was examined next by meta-analysis." (PMID 22844464, 2012). "TBX2 gene amplification has previously been reported in aggressive BRCA1-related breast cancers." (PMID 22844464, 2012). "We therefore asked whether the EMT-inducing and pro-invasive abilities of TBX2 that we observed in normal breast epithelial cells, could also play a role in human breast cancer." (PMID 22844464, 2012). "In addition, we identified TBX2 overexpression in two metaplastic tumor-derived breast carcinoma cell lines, MDA-MB-435 and MDA-MB-157, which we found to express higher median levels of TBX2 than most other breast tumors." (PMID 22844464, 2012). "Moreover, the ER-negative basal breast carcinoma cell line SUM52 displayed abundant TBX2 protein and mRNA expression, as well as modest gene amplification levels, consistent with previous Fluorescence In Situ Hybridization (FISH) data." (PMID 22844464, 2012). "In addition, TBX2 is a key oncogenic molecule in breast cancer." (PMID 38965548, 2024). "Overall these in vitro and in vivo data provided evidence that specific targeting of LSD1, at the H3 allosteric site via SP-2509, can lead to effective upregulation of TSGs and may be a viable therapeutic option for exploiting TBX2 dependency in breast cancers." (PMID 35687133, 2022). "The physiological subcellular localization of TBX21 is regulated by PD1 in T-cells and aberrant enhancement of nuclear import from the cytoplasm has been reported for TBX2 in breast cancer cells, indicating that this type of regulation may play a role for the related TBX3 as well." (PMID 34807923, 2021). "In breast cancer cells, stress signals initiated by ultraviolet-C irradiation promoted the phosphorylation of TBX2 by p38 MAP kinase, resulting in an increase in TBX2 protein levels, nuclear localisation and its ability to repress p21Cip1." (PMID 39912718, 2025). "Depleting TBX2, Sp1 or CoREST members resulted in the de-repression of NDRG1 which was accompanied by reduced breast cancer cell viability and colony-forming ability." (PMID 39912718, 2025). "Recently, TBX2 was also shown to repress NDRG1 and CST6 in breast cancer by recruiting a CoREST repression complex (LSD1, ZNF217 and HDAC1) to their promoters." (PMID 39912718, 2025). "TBX2 is highly expressed in a variety of tumors, such as hepatocellular carcinoma (HCC), gastric cancer (GC), glioblastoma (GBM), and breast cancer." (PMID 38965548, 2024).
breast carcinoma (continued). "TBX2/3 can promote epithelial–mesenchymal transition (EMT) and invasive cell behavior in melanoma and breast cancer cells and in heterospecific epithelia." (PMID 26579496, 2015). "The closely related T-box transcription factors TBX2 and TBX3 are frequently overexpressed in melanoma and various types of human cancers, in particular, breast cancer." (PMID 26579496, 2015). "For instance, some of the genes enriched in canine iUC samples i.e., PPARG, TBX2, ERBB2, ERBB3 are genes indicative of luminal subtypes of breast cancer in humans." (PMID 26352142, 2015). "TBX2/3 can promote epithelial-mesenchymal transition (EMT) and invasive cell behavior in melanoma and breast cancer cells." (PMID 25344916, 2014). "This is significant because TBX2, a homologue of TBX3, was shown to be a powerful pro-proliferative factor in melanoma and breast cancer cell lines which express both TBX2 and TBX3 and there has been an indication that TBX2 and TBX3 can repress each other." (PMID 24098938, 2013). "It has previously been shown that Cdkn1a expression is elevated on inactivation of endogenous Tbx2 in the murine B16 melanoma and the human MCF-7 breast cancer cell line." (PMID 23341776, 2013). "Concordant with this phenotype, mRNA expression of epithelial E-cadherin and ZO1 was enhanced, whereas transcription of mesenchymal genes (N-cadherin, Vimentin, Fibronectin, MMP3) was reduced in TBX2-depleted MDA-MB-435 and MDA-MB-157 breast cancer cells." (PMID 22844464, 2012). "Inhibition of TBX2 further led to reduced tumor cell migration in both MDA-MB-435 and MDA-MB-157 breast carcinoma cell lines." (PMID 22844464, 2012). "For example, TBX2 interacts with and requires early growth response 1 (EGR1) to inhibit the tumour suppressor genes N-myc downstream-regulated gene 1 (NDRG1) and cysteine protease inhibitor cystatin 6 (CST6) to promote breast cancer cell proliferation." (PMID 39912718, 2025). "Indeed, studies have reported dysregulation of crucial fetal mammary developmental genes [e.g., T-box transcription factors (TBX2 and TBX3)] in human breast cancer cells in vitro." (PMID 40001874, 2025). "In addition, TBX2 and TBX3 have been reported to be overexpressed in certain cancer types, including endometrial, cervical, ovarian, breast carcinoma." (PMID 38413457, 2024). "TBX2 started mechanisms of normal growth control by recruiting a series of inhibitory compounds to combine with reactive promoter of EGR1, which led to uncontrolled proliferation of breast cancer cells." (PMID 38413457, 2024). "TBX2 amplification has been reported to be enriched in BRCA1 mutant breast cancers (which are predominantly ERα-negative) but the in vitro models we have used are predominantly ERα-positive." (PMID 35687133, 2022). "TBX2 may be involved in malignant progression as its overexpression correlates with advanced tumor stages and with aggressive, hereditary BRCA1/2 breast cancers." (PMID 35846378, 2022). "TBX2-G9a-PRC2 catalyzes the H3K9me2/3 methylation of histone H3 on the promoter of N-Myc downstream-regulated gene 1 protein (NDGR1), suppressing its expression and increasing the cell proliferation of breast cancer cells." (PMID 35740522, 2022). "Exogenous expression of wild-type CST6 in TBX2 expressing breast cancer cells resulted in significant apoptosis whilst non-tumorigenic breast cells remain unaffected." (PMID 24742492, 2014). "Exogenous expression of CST6 in TBX2-expressing breast cancer cells resulted in significant apoptosis whilst non-tumorigenic breast cells remained unaffected." (PMID 24742492, 2014). "We show that exogenous expression of wild-type CST6 induces apoptotic effects in TBX2 expressing breast cancer cells but not in non-tumorigenic breast cells." (PMID 24742492, 2014).
breast carcinoma (continued). "Furthermore, senescence suppression by TBX2 in human cells depends on the physical interaction of TBX2 with tumor suppressive TFs, for example EGR1 in breast cancer cells, and PML in fibroblasts." (PMID 22844464, 2012). "Significantly, a role of TBX2 in oncogenic EMT and malignant breast cancer progression is further suggested by our finding that TBX2 mRNA levels in clinical human breast cancer specimen were highest in rare EMT-enriched tumors of the ‘claudin-low’ and metaplastic breast tumor subtypes." (PMID 22844464, 2012). "By modeling aberrant gain-of-function of TBX2 in breast cancer through ectopic expression of TBX2 in non-malignant mammary epithelial cell lines (HC11, MCF10A), we demonstrated that TBX2 alone is sufficient to induce EMT and cell invasion." (PMID 22844464, 2012). "In discrepancy with our results, previous studies have indicated that TBX2 knockdown in MCF7 breast carcinoma and human melanoma cell models did not diminish tumor cell invasion or repress endogenous E-cadherin expression." (PMID 22844464, 2012). "Amplification of TBX2 has been reported in a subset of breast cancer patients; however, a direct link between LPA signalling and TBX2 levels has not been shown in breast cancer." (PMID 20234370, 2010). "T-box transcription factors (TBX2 and TBX3), WNT signaling, fibroblast growth factors (FGFs), bone morphogenetic proteins (BMPs), and parathyroid hormone-related protein (PTHrP) are among the molecular players identified in both mammary gland development and breast cancer biology." (PMID 40001874, 2025). "The importance of ZNF217 for TBX2-CoREST repression may also explain why disruption of ZNF217 interactions within the complex by SP-2509 was effective in de-repressing TSGs and inhibiting breast cancer cell proliferation." (PMID 35687133, 2022). "We found that TBX2 was variably expressed across the different molecular subtypes of breast cancer, largely independent of estrogen receptor (ER) status and tumor grade, with the highest expression levels among the rare, aggressive ‘claudin-low’ subtype of breast cancer and lowest in basal tumors." (PMID 22844464, 2012). "However none of the four basal-subtype ER-negative BRCA1-deficient breast carcinoma cell lines (HCC1937, MDA-MB-436, SUM149, and SUM1315) we studied expressed TBX2 protein at detectable levels or exhibited TBX2 gene amplification." (PMID 22844464, 2012). "Treatment with BIX-01294 reduces cell proliferation, and this is observed to an even greater degree upon combination with DN-TBX2, a mutant TBX2 protein containing an absent T-box domain, suggesting that G9a and TBX2 may have a synergistic role in driving breast cancer cell proliferation." (PMID 35740522, 2022). "The same study showed that the TBX2-CoREST complex transcriptionally represses the long non-coding RNA LINC00111 through a region containing a CREM-binding motif, leading to breast cancer cell growth and survival." (PMID 39912718, 2025). "Moreover, TBX2 is marked by a SE in all investigated NB cell lines, but not in the human neural crest line (hNCC) and the MCF-7 breast cancer cell line." (PMID 30451831, 2018). "Taken together these data indicated that although TBX2 and LSD1 did not have a mutual requirement for protein stability, the interaction between the two factors may be important for repression of TBX2 target genes and maintenance of breast cancer cell growth." (PMID 35687133, 2022). "Importantly, TBX2 and TBX3 may additionally play non-redundant roles in breast cancers." (PMID 35846378, 2022).
melanoma (27 papers, 2006 to 2025). A malignant, usually aggressive tumor composed of atypical, neoplastic melanocytes. "Consistent with the correlations between mutations activating PI3K signaling and TBX2 in human and mouse tumors, TBX2 protein levels were decreased in three human melanoma cell lines using two different PI3K inhibitors: LY294002 or GDC0941." (PMID 34819350, 2021). "Nevertheless, our results do provide compelling evidence that TBX2 is up-regulated by PI3K signaling that is associated with melanoma progression." (PMID 34819350, 2021). "Collectively, these observations place the antisenescence transcription factor TBX2 downstream from PI3K signaling that mediates senescence bypass in BRAF mutated melanoma." (PMID 34819350, 2021). "We also examined the levels of Tbx2 and Tbx3, which have been associated with E-cadherin downregulation in melanoma cells." (PMID 22911700, 2012). "In this realm, the transcription factor TBX2 overexpression has been directly linked to several cancers, including rhabdomyosarcoma, breast, melanoma, nasopharyngeal, and prostate cancers." (PMID 32195221, 2020). "For this, we chose the B16 mouse melanoma cell line because it is readily susceptible to senescence after Tbx2 depletion and does not express Tbx3, a highly related T-box factor expressed in many human melanoma cell lines that can potentially regulate similar genes to Tbx2." (PMID 34819350, 2021). "With this in mind, we explored the potential of PO, which was previously shown to inhibit TBX2 and TBX3 in TBX2‐/3‐dependant melanoma and rhabdomyosarcoma cells, to inhibit levels of these two proteins in PDAC cells." (PMID 40717225, 2025). "PO was also shown to inhibit cell viability in several cancer cell lines, including two PDAC cell lines and was recently reported to inhibit TBX3, and its homologue TBX2, and to exert anti‐cancer activity in TBX2‐/3‐dependent melanoma and rhabdomyosarcoma." (PMID 40717225, 2025). "In melanoma cells, TBX2 recruits HDAC1 to the p21 promoter, silencing its expression and enabling continued proliferation—even in the absence of CDKN2A, a well-known tumor suppressor frequently mutated in melanoma." (PMID 40723431, 2025). "The overexpression of TBX2 in melanoma and other cancers such as breast, pancreatic, and liver cancer further supports its function as a key transcriptional repressor involved in maintaining a proliferative, pigmentation-prone state." (PMID 40723431, 2025). "TBX2, a member of the T-box family of transcription factors, has stronger support in the literature in both melanogenesis and melanoma biology." (PMID 40723431, 2025). "The overexpression of TBX2 has been shown to maintain proliferation and suppress senescence in melanomas." (PMID 40723431, 2025). "This positions TBX2 as an attractive target for therapeutic intervention in a wide range of carcinomas, sarcomas and melanoma." (PMID 39912718, 2025). "This is an important finding as it shows that these three drugs maintain their ability to downregulate either TBX2, TBX3 or both in TBX2/TBX3‐dependent non‐melanoma cancer cell lines." (PMID 39403898, 2024). "TBX2 promotes E2F1 expression in melanoma by directly binding to it, a key anti-aging cell cycle regulator." (PMID 38965548, 2024). "TBX19 itself has not been implicated in melanoma, but it has been linked to lymph node metastasis in colorectal cancer and TBX2, another member of the T-Box family, is involved in melanoma proliferation." (PMID 36894939, 2023). "Consistent with the GSEA, Tbx2 depletion using three different siRNAs in mouse B16 melanoma cells led to a strong reduction of E2f1 protein expression." (PMID 34819350, 2021).
melanoma (continued). "To confirm this, we used independent siRNAs to deplete Tbx2 from B16 melanoma cells and used flow cytometry to compare their cell cycle profile with untransfected cells or those transfected with a control siRNA." (PMID 34819350, 2021). "Significantly, we also reveal that TBX2 directly represses PTEN in melanoma, a result consistent with observations in rhabdomysosarcoma and nasopharyngeal carcinoma, where TBX2-mediated repression of PTEN mRNA expression has been observed." (PMID 34819350, 2021). "To gain an insight into the role of TBX2 in melanoma, we aimed to identify the repertoire of TBX2-bound target genes using chromatin immunoprecipitation followed by high-throughput sequencing (ChIP-seq)." (PMID 34819350, 2021). "After urothelial cancer, melanoma exhibits the second highest levels of TBX2 mRNA among all cancers." (PMID 34819350, 2021). "Here, using melanoma as a model, we show that TBX2 lies downstream from PI3K signaling and that TBX2 binds and is required for expression of E2F1, a key antisenescence cell cycle regulator." (PMID 34819350, 2021). "In melanoma, T-box 2 (Tbx2) downregulates expression of the cell cycle inhibitor CDKN1A (p21) by targeting HDAC1 to its promoter." (PMID 32042336, 2020). "This is supported by the finding that TBX2 or TBX3 are overexpressed/amplified in melanoma and various types of cancer and that the degree of overexpression correlates with invasiveness, distant metastasis, and poor prognosis." (PMID 26579496, 2015). "In melanoma, TBX2 (and its paralog TBX3) directly repress E-cad by binding to its promoter, causing enhanced invasiveness." (PMID 25344916, 2014). "The TBX2 gene is deregulated in melanoma, breast, and pancreatic cancers where it suppresses senescence through the repression of cyclin-dependent kinase inhibitors, p19 and p21." (PMID 23984174, 2013). "The antifungal piroctone olamine, previously identified as a TBX2‐/3‐targeting drug in melanoma and rhabdomyosarcoma, inhibited the levels of TBX2 and TBX3 and recapitulated the phenotypes observed when they were knocked down in 2D and 3D PDAC cell culture models." (PMID 40717225, 2025). "Importantly, CA5 was found to display potent cytotoxicity against TBX2-driven melanoma, breast and RMS cells, and in melanoma, this was shown to involve its ability to target TBX2." (PMID 39912718, 2025). "Similarly in melanoma, Tbx2 overexpression directly repressed p21CIP1 which inhibited the onset of replicative senescence and promoted cell cycle progression." (PMID 39912718, 2025). "Indeed, chromatin immunoprecipitation sequencing (ChIP-seq) carried out in melanoma revealed that, while target genes repressed by TBX2 typically involve T-elements, E-box motifs commonly mediated its activation of its target genes." (PMID 39912718, 2025). "In melanoma, TBX2 was shown to promote proliferation and senescence bypass downstream of the PI3K signalling pathway where it activates the expression of the anti-senescence cell cycle regulator E2F1 and represses PTEN, a negative regulator of the AKT/PI3K pathway." (PMID 39912718, 2025). "Due to a lack of reliable and high‐grade antibodies against TBX2 and TBX3 for immunofluorescence, this study used a tetracycline‐on (Tet‐On) system that enabled the inducible expression of 3XFLAG‐tagged TBX2 or 3XFLAG‐tagged TBX3 in the 501mel human melanoma cell line." (PMID 39403898, 2024). "Endogenous TBX2 is critical for maintaining melanoma cell proliferation and inhibiting senescence." (PMID 38965548, 2024). "We next determined whether the 3 ‘hit’ drugs could inhibit melanoma and rhabdomyosarcoma cell viability through negatively regulating TBX2/3 levels." (PMID 39403898, 2024). "The results revealed that mouse melanomas with activated Nras, which can activate PI3K signaling, expressed higher levels of Tbx2 than those with the BrafV600E mutation, and that in both NrasQ61K or BrafV600E melanomas, loss of Pten increased Tbx2 expression." (PMID 34819350, 2021).